SCGB1D2 (secretoglobin family 1D member 2)
Description:
May bind androgens and other steroids, may also bind estramustine, a chemotherapeutic agent used for prostate cancer. May be under transcriptional regulation of steroid hormones.
Synonyms: LPNB; LPHB; LIPB
Tractability: Antibody: UniProt places it where antibodies can reach, with high confidence; UniProt predicts a signal peptide or a membrane-spanning region; its Gene Ontology location is reachable by antibodies, with medium confidence.
Gene: Protein-coding gene on chromosome 11 (62,242,239 to 62,244,812, forward strand). Ensembl gene ENSG00000124935.
Subcellular location: Secreted
Gene Ontology:
Cellular component: extracellular region
Genetic constraint (gnomAD): Loss-of-function variants: 10 observed, 9.6 expected, observed/expected ratio (o/e) 1.04, 90% interval 0.64 to 1.71. That is too few expected variants to judge how well the gene tolerates losing a copy. Missense variants: 104 observed, 97.59 expected, observed/expected ratio (o/e) 1.07, 90% interval 0.91 to 1.25. Synonymous variants: 37 observed, 42.06 expected, observed/expected ratio (o/e) 0.88, 90% interval 0.68 to 1.16.
Homologues: Orthologues: chimpanzee SCGB1D2 (97% identical), macaque SCGB1D2 (70% identical), rabbit SCGB1D1 (54% identical), rabbit SCGB1D (51% identical), rat Scgb1d2 (49% identical), pig SCGB1D1 (48% identical), rat Scgb1d4 (44% identical), rat AABR07006242.1 (40% identical). Paralogues in human: SCGB1D1 (59% identical), SCGB1D4 (51% identical).
Diseases named in the same sentence as SCGB1D2 in open-access papers:
SCGB1D2 is named in the same sentence as 26 diseases in open-access papers, as found by Europe PMC text mining. Sharing a sentence is not in itself a finding about the gene and the disease. The quoted sentences say what the papers report.
breast carcinoma (11 papers, 2006 to 2025). "Three variants, rs116638271 in ALDH3B2, rs77274510 in RP11-703H8.9, and rs117564384 in SCGB1D2 in the chromosome 11q13 region were significantly associated with ER+ breast cancer after correction for multiple testing." (PMID 27708667, 2016). "Among them, AZGP1 and CRISP3 are associated with breast cancer invasiveness, while SCGB2A2 and SCGB1D2 serve as common markers for disseminated tumor cells (DTCs)." (PMID 40838787, 2025). "Lipophilin B (SCGB1D2), a member of the secretoglobin superfamily, is expressed almost specifically in breast tissue and is upregulated in breast cancer and female genital tract tumors." (PMID 32602849, 2020). "Overexpression of mammaglobin 1 (SCGB2A2)/lipophilin B (SCGB1D2) and PIP is linked to good prognosis in ovarian and breast cancer." (PMID 31360859, 2018). "Mammaglobin A (SCGB2A2) and lipophilin B (SCGB1D2) expression was analyzed by northern blot in a panel of 4 matched breast cancer/normal breast tissue pairs." (PMID 16603086, 2006). "Mammaglobin A (SCGB2A2) and lipophilin B (SCGB1D2), two members of the secretoglobin superfamily, are known to be co-expressed in breast cancer, where their proteins form a covalent complex." (PMID 16603086, 2006). "While SCGB2A2 and SCGB1D2 are reported as markers of breast cancer, their roles in human brain have not been exhaustively investigated." (PMID 40033360, 2025).
Lyme disease (2 papers, 2024). Lyme disease (named after the towns in the USA where the disease was first identified) is a bacterial infection caused by Borrelia burgdorferi. "Here, the authors discover a risk locus in the gene encoding the protein Secretoglobin family 1D member 2, which is expressed in skin and affects infection by the bacteria that causes Lyme disease in vitro and in vivo." (PMID 38503741, 2024). "Using epidemiological and genetic data from FinnGen and Estonian Biobank, we identify two previously known variants and an unknown common missense variant at the gene encoding for Secretoglobin family 1D member 2 (SCGB1D2) protein that increases the susceptibility for Lyme disease." (PMID 38503741, 2024). "It is noteworthy that this SCGB1D2 P53L variant appears quite specific for Lyme disease and has not been previously reported as associated with any other disease, phenotype, or infection." (PMID 38503741, 2024). "Additionally, the results indicate SCGB1D2 as a host defense mechanism against Borrelia infection and against Lyme disease." (PMID 38503741, 2024). "Together, these data suggest that SCGB1D2 is a host defense factor present in the skin, sweat, and other secretions which protects against Bb infection and opens an exciting therapeutic avenue for Lyme disease." (PMID 38503741, 2024). "To investigate the impact of SCGB1D2 on Bb establishing infection in vivo, we injected C57BL/6 J female mice aged at 10 weeks at the time of infection intradermally with Bb incubated with either SCGB1D2 or SCGB3A1, a secretoglobin that does not associate with Lyme disease." (PMID 38503741, 2024).
melanoma (2 papers, 2018 to 2021). A malignant, usually aggressive tumor composed of atypical, neoplastic melanocytes. "C1QB, CXCL9, CXCL10, DFNA5 (GSDME), FCGR1B, and PRAME were increased in melanoma, and SCGB1D2 was decreased in melanoma, compared to dysplastic nevi or nevi that progressed to melanoma." (PMID 35008167, 2021). "SCGB1D2 showed a decrease in expression with melanoma progression with a coefficient of −0.32, consistent with a prior study." (PMID 35008167, 2021).
ovarian carcinoma (2 papers, 2013 to 2025). A malignant neoplasm originating from the surface ovarian epithelium. "Additionally, SCGB1D2 upregulation has been reported in both breast and ovarian cancers, supporting its broader role as a potential tumor suppressor." (PMID 41262902, 2025).
endometrial cancer (1 paper, 2025). Primary or metastatic malignant neoplasm involving the endometrium (mucous membrane that lines the endometrial cavity). "Kaplan Meier plots using TCGA Endometrial Cancer database revealed that high mRNA expression of SCGB1D2, CD52, GNG2, GDNF, and SCUBE1correlated with favorable prognosis in EC patients (n=547)." (PMID 41262902, 2025).
tumor (9 papers, 2006 to 2025). "Mammaglobin A (SCGB2A2) and lipophilin B (SCGB1D2) expression were analyzed by dot blot analysis using Clontech's "Matched Tumor/Normal Array" (MTNA) and "Cancer Profiling Array I" (CPA) for each gene." (PMID 16603086, 2006). "Genes with reported anti-tumor functions, including SCGB1D2 (Secretoglobin Family 1D Member 2, lipophilin B), FKBP5, CD52, DLK1, GALNT9, GNG2, GDNF, and TMEM35A, were significantly upregulated after CUDC-907 + MPA treatment and validated by RT-PCR." (PMID 41262902, 2025). "Immunohistochemistry of primary tumor tissue was performed for eight proteins: COL6A6, DCD, GBP4, KLHL41, KRT9, PIP, SCGB1D2, SCGB2A2." (PMID 34757537, 2022).
infection (1 paper, 2024). The state of being infected such as from the introduction of a foreign agent such as serum, vaccine, antigenic substance or organism. "Pre-incubation of either ML23 or N40D10/E9 strains of Bb with SCGB1D2 protein prevented Bb from establishing infection." (PMID 38503741, 2024). "Finally, using an in vivo murine infection model we show that recombinant SCGB1D2 prevents infection by Borrelia in vivo." (PMID 38503741, 2024).
SCGB1D2 also shares sentences with these, for which no sentence is quoted: cancer (3 papers); breast tumor (2); bacterial diseases (1); cervical adenocarcinoma (1); cervical cancer (1); dysplastic nevi (1); erysipelas (1); gynecologic cancer (1); gynecologic tumors (1); ichthyosis (1); lung carcinoma (1); pituitary adenomas (1); prostate carcinoma (1); rectal tumors (1); scarlet fever (1); Sepsis (1); skin infection (1); syphilis (1); tick-borne encephalitis (1).